LONP1 (lon peptidase 1, mitochondrial)
Diseases named in the same sentence as LONP1 in open-access papers (continued):
Sharing a sentence is not in itself a finding about the gene and the disease.
Obesity (3 papers, 2023 to 2024). Accumulation of substantial excess body fat. "Next, we evaluated the possible effect of acute muscle LONP1 deletion in the context of HFD-induced obesity." (PMID 39221030, 2024). "This suggests that a homeostatic mechanism to maintain mitochondrial function and systemic metabolism (including glucose) is initiated by increasing the expression of LONP1 in human VAT in obesity." (PMID 37569389, 2023). "Interestingly, in silico analysis of the promoters of the Hsp60, Hsp10, and Lonp1 genes revealed that these genes can be regulated by MAPK signaling, which has been linked to the development of obesity and MetS." (PMID 37569389, 2023). "Considering that the incidence of MetS is increasing every year and there are not enough potential therapeutic targets to address this important public health problem, investigating the role of LonP1 in obesity and MetS is an urgent task for the scientific community." (PMID 37569389, 2023). "However, the function of LonP1 in obesity and MetS in vivo is unknown." (PMID 37569389, 2023). "Furthermore, following Lonp1 ablation, muscles are forced to secrete myokines, especially FGF21 and GDF15, to exert endocrine effects, which can contrast diet-induced obesity and generates a positive effect on metabolism." (PMID 36978846, 2023). "In addition, Lonp1 skeletal muscle-specific ablation upon HFD feeding triggers the induction of several UPRmt markers, suggesting that muscle UPRmt signals may have a protective effect, as they can regulate the communication between adipose tissue and the liver and alleviate dietary obesity." (PMID 36978846, 2023).
pancreatic cancer (3 papers, 2022 to 2024). "As shown in pancreatic cancer cells, LONP1 knockdown increases the expression of the epithelial marker claudin-1 and decreases the mesenchymal marker vimentin as well as transcription factors snail and slug." (PMID 35864539, 2022).
Parkinson disease (3 papers, 2021 to 2024). A progressive degenerative disorder of the central nervous system characterized by loss of dopamine producing neurons in the substantia nigra and the presence of Lewy bodies in the substantia nigra and locus coeruleus. "Indeed, dysfunction of LONP1 in mitochondria has been associated with a number of neurological disorders including Parkinson’s disease, Friedreich ataxia, and amyotrophic lateral sclerosis." (PMID 33668863, 2021). "LONP1 and CLPXP improve PD-related phenotypes, respectively, by degrading PINK1 and parkinson disease protein 7, which are involved in the pathological process of PD, and reducing the accumulation of α-synuclein variant A53T." (PMID 39164792, 2024).
status epilepticus (3 papers, 2019 to 2022). Status epilepticus is defined as a continuous seizure lasting more than 30 min, or two or more seizures without full recovery of consciousness between any of them. "MQC-related serine peptidase LONP1 is up-regulated in the mitochondria during status epilepticus (SE), and LONP1 knockdown enhances SE-induced mitochondrial apoptosis in neuron." (PMID 36578825, 2022).
Ureteral obstruction (3 papers, 2023 to 2024). Obstruction of the flow of urine through the ureter. "84-B10 is a novel 3-phenylglutaric acid derivative that can activate the mitochondrial protease, Lon protease 1 (LONP1), and may protect against cisplatin-induced AKI and unilateral ureteral obstruction- or 5/6 nephrectomy [5/6Nx]-induced CKD model." (PMID 38202741, 2023).
breast carcinoma (2 papers, 2022). "Many of those hits were supported by literature, whereby some hits were so far overlooked in the context of breast cancer (e.g., Lonp1, Uspl1) or cancer in general (e.g., Psmd13, Tysnd1)." (PMID 36313646, 2022). "In colon, liver, and breast cancer cells, CDDO induces depolarization, increases mitochondrial ROS, and alters mitochondrial morphology by targeting LonP1, thereby promoting apoptosis in cancer cells." (PMID 36362158, 2022).
cataract (2 papers, 2018 to 2023). Partial or complete opacity of the crystalline lens of one or both eyes that decreases visual acuity and eventually results in blindness. "Although our patient was heterozygous for the variant and did not present mild dysmorphia, mutations in LONP1 associated with non-syndromic pediatric cataracts present in heterozygosis have been described in the literature." (PMID 37511188, 2023). "The proband in the family OFT-00247 was heterozygous for the mutation in the LONP1 gene, (OMIM 605490), NM_004793.3:c.1939G>A:p.(Glu647Lys), inherited from his father, who did not have lens opacity." (PMID 37511188, 2023).
Friedreich ataxia (2 papers, 2021 to 2023). An inherited condition that affects the nervous system and causes movement problems. "The expression and activity of Lonp1 were also studied in a mouse model of Friedreich ataxia (FRDA), a rare disease characterized by progressive cardiomyopathy and ataxia with a deficiency in mitochondrial frataxin, which is essential for Fe-S clusters assembly." (PMID 36978846, 2023).
gastric cancer (2 papers, 2022 to 2024). A primary or metastatic malignant neoplasm involving the stomach. "The hub gene-based risk model (DUSP1/TNF/NOX4/LONP1) shows promise as an overall survival predictor in gastric cancer." (PMID 38758860, 2024). "In response to H. pylori infection, LONP1 expression increases in gastric cancer cells, and LONP1 is necessary for H. pylori-induced gastric cell proliferation and promotes H. pylori-induced metabolic switch to glycolysis." (PMID 35864539, 2022). "Studies in gastric cancer demonstrate that LONP1 knockdown reduces mitochondrial respiration." (PMID 35864539, 2022).
hepatocellular carcinoma (2 papers, 2022 to 2024). A malignant tumor that arises from hepatocytes. "A previous study further found that when the toxic agent diphenylarsinic acid was added to hepatocellular carcinoma cells, LONP1 promoted the degradation of GAC, while the accumulation of insoluble aggregates was observed in LONP1-knockdown cells." (PMID 36362158, 2022).
ischemia (2 papers, 2019 to 2023). A hypoperfusion of the BLOOD through an organ or tissue caused by a PATHOLOGIC CONSTRICTION or obstruction of its BLOOD VESSELS, or an absence of BLOOD CIRCULATION. "Overexpression of Lonp1 in transgenic mice hearts reduced protein carbonylation and lipid peroxidation, known cardiac I/R injury hallmarks in vivo during ischemia and early reperfusion." (PMID 36978846, 2023). "Thus, these lines of evidence place Lonp1 as one of the mediators of IPC cardioprotection by attenuating ROS- and ischemia-induced damage and reducing infarct size upon I/R injury." (PMID 36978846, 2023).
Leigh syndrome (2 papers, 2018 to 2020). "Recessive variants in the LONP1 gene have been found to cause Leigh syndrome and the syndrome of cerebral, ocular, dental, auricular, and skeletal anomalies." (PMID 33426505, 2020).
oral cancer (2 papers, 2022). "Indeed, Lonp1 upregulation was found in several tumors, including lung, cervical, and oral cancer, associated with a worsened prognosis." (PMID 36313646, 2022). "An association has also been noted between NCLX and LonP1 levels in oral cancer tissue samples." (PMID 36362158, 2022). "The molecular chaperone activity of LonP1 is also involved in the emergence and progression of oral cancers." (PMID 36362158, 2022). "Recently, the LonP1-NCLX axis has been found to promote cisplatin resistance in oral cancer cells." (PMID 36362158, 2022). "In oral cancer-derived cell lines (OEC-M1 and FADU), the upregulation of LonP1 triggers ROS production, which further promotes proliferation via Ras-ERK signaling and migration and invasion via the ERK and p38 MAPK pathways." (PMID 36362158, 2022). "Inhibitors of LonP1 and NCLX may be used as potential adjuvants to cisplatin therapy to avoid chemoresistance and enhance the curative effect in patients with oral cancer." (PMID 36362158, 2022). "In the laboratory, oral cancer-derived cells and tissue samples from oral squamous cell carcinoma (OSCC) showed a significant upregulation of LonP1 compared to cells or tissues without tumors." (PMID 36362158, 2022).
osteoarthritis (2 papers, 2022 to 2024). A noninflammatory degenerative joint disease occurring chiefly in older persons, characterized by degeneration of the articular cartilage, hypertrophy of bone at the margins and changes in the synovial membrane. "The mitochondrial protein hydrolase Lon Protease 1 (LONP1) acts as a molecular chaperone in mitochondria, and its downregulation with age contributes to osteoarthritis through mitochondrial dysfunction." (PMID 38225636, 2024). "In osteoarthritis, chondrocytes with a knockdown of LonP1 were found to exhibit severe inflammation." (PMID 36362158, 2022). "In osteoarthritis, LONP1-knockdown chondrocytes have been found to exhibit down-regulated OXPHOS (a significant decline in the basal and maximal O2 consumption rate [OCR]) and further promote the progression of inflammation." (PMID 36362158, 2022). "In chondrocytes, the knockdown of LonP1 leads to severe mitochondrial damage, and the activation of the PINK1/Parkin pathway induces mitophagy and exacerbates osteoarthritis." (PMID 36362158, 2022).
osteoporosis (2 papers, 2024 to 2025). A condition of reduced bone mass, with decreased cortical thickness and a decrease in the number and size of the trabeculae of cancellous bone (but normal chemical composition), resulting in increased fracture incidence. "Subsequent investigations revealed that imbalanced skeletal muscle mitochondrial proteostasis caused by muscle LONP1 deficiency results in severe osteoporosis." (PMID 39221030, 2024). "In summary, this study reveals that WSTLZTD ameliorates osteoporosis by regulating macrophage senescence via LONP1, thereby suppressing cGAS/STING pathway activation in BMSCs to enhance osteogenic differentiation (Created in BioRender)." (PMID 40719285, 2025). "Our study provides compelling evidence that targeted disruption of LONP1 in skeletal muscle results in severe mitochondrial disorders, leading to decreased muscle size and strength and an accelerated aging phenotype typified by osteoporosis." (PMID 39221030, 2024). "In general, our finding illuminates the vital role of LONP1-mediated mitochondrial proteostasis in preserving bone metabolic equilibrium, offering potential insights into the intricate interplay between mitochondria and bone health and promising therapeutic avenues for osteoporosis treatment." (PMID 39221030, 2024). "WSTLZTD potentially modulate macrophage senescence via LONP1, which subsequently suppresses the activation of the cGAS/STING pathway in BMSCs, ultimately promoting their osteogenic differentiation and ameliorating osteoporosis." (PMID 40719285, 2025).
polycystic ovary syndrome (2 papers, 2025). A disorder that manifests as multiple cysts on the ovaries. "Notably, the interaction between LONP1 and cytochrome P450 family 11 subfamily A member 1 has been implicated in polycystic ovary syndrome (PCOS), and pharmacological interventions such as artemisinin have been shown to alleviate PCOS phenotypes by enhancing this interaction." (PMID 41256733, 2025). "Conversely, LONP1 activators, including Artemisinin derivatives and 84-B10, restore mitochondrial function and protect against conditions such as polycystic ovary syndrome (PCOS) and acute kidney injury (AKI)." (PMID 40305312, 2025).
prostate adenocarcinoma (2 papers, 2023 to 2025). "However, over a follow-up period of over 12 months, no development of prostate adenocarcinoma was detected, indicating that Lonp1 knockin alone was insufficient to drive PCa." (PMID 39971909, 2025).
prostate tumors (2 papers, 2025). "The co-expression of ClpP and LONP1 in prostate tumors, both located on chromosome 19q13, suggests a coordinated oncogenic stress–adaptive axis." (PMID 41155556, 2025). "Collectively, our study demonstrated that the overexpression of LONP1 in both murine prostate tumors and human PCa cells results in the inhibition of mitochondrial respiratory chain complex I activity." (PMID 39971909, 2025). "However, our research demonstrated that the overexpression of LONP1 in mouse prostate tumors inhibits mitochondrial complex I activity, as evidenced by widespread decreases in various subunits at both the transcript and protein levels." (PMID 39971909, 2025).
adenoma (1 paper, 2018). A neoplasm arising from the epithelium. "LonP1 was almost absent in normal mucosa, gradually increased from aberrant crypt foci to adenoma, and was most abundant in CRC." (PMID 30038898, 2018).
aristolochic acid nephropathy (1 paper, 2025). "This role of 84-B10 as an activator of LONP1 has been further confirmed in another study, where it was tested against aristolochic acid nephropathy (AAN), a form of renal toxicity linked to Aristolochiaceae-derived aristolochic acids (AAs)." (PMID 40305312, 2025).
cardiomyopathy (1 paper, 2023). A disease of the heart muscle or myocardium proper. "Moreover, during late-stage cardiomyopathy, a further Lonp1 induction and Fe-S protein levels reduction in the heart were observed, suggesting that Fe-S proteins are substrates of Lonp1 activity." (PMID 36978846, 2023).
colon adenocarcinoma (1 paper, 2022). "This suggests, that besides the total expression level of Lonp1, the relative expression of the isoforms can impact the patients’ survival, as we can see, for example, in colon adenocarcinoma, head, and neck squamous cell carcinoma, and lung squamous cell carcinoma." (PMID 36497197, 2022).
colorectal tumors (1 paper, 2022). "A deficiency in LONP1 expression in mice inhibits the formation and growth of azoxymethane- and dextran sulfate-induced colorectal tumors." (PMID 35864539, 2022). "In vivo, LONP1 knockdown inhibits the growth of prostate and colorectal tumors and inhibits the formation of metastatic lesions from primary prostate and melanoma tumors." (PMID 35864539, 2022).
congenital diaphragmatic hernia (1 paper, 2023). A posterolateral defect of the diaphragm that allows passage of abdominal viscera into the thorax, leading to respiratory insufficiency and persistent pulmonary hypertension with high mortality. "Recently, a different set of mutations of the Lonp1 human gene has been shown to cause congenital diaphragmatic hernia (CDH), whereby abnormal development of the diaphragm before birth leads to defects ranging from a weakened area in the diaphragm to its full absence." (PMID 36978846, 2023).
cyst (1 paper, 2025). A sac-like closed membranous structure that may be empty or contain fluid or amorphous material. "Previous studies showed that Shhcre-mediated inactivation of Lonp1 in lung endoderm led to drastic lung hypoplasia with the replacement of lobes by cyst-like structures." (PMID 41049046, 2025).
fibrosarcoma (1 paper, 2022). A malignant mesenchymal fibroblastic neoplasm affecting the soft tissue and bone. "Finally, while LonP1 siRNA was not possible to significantly interfere with cell movement, treatment with CDDO-Me was found to decrease the motility of fibrosarcoma and metastatic melanoma cells, suggesting that LonP1 could be a potential target for cancer therapy in these cells." (PMID 35456042, 2022).
fibrosis (1 paper, 2023). the formation of excess fibrous connective tissue in an organ or tissue in a reparative or reactive process. "With the UUO model, Lonp1‐specific overexpression in renal proximal tubules significantly attenuated tubular brush border loss, tubule atrophy, cellular infiltration, and tubulointerstitial fibrosis in the kidneys determined by Masson's trichrome and Sirius red staining." (PMID 36629048, 2023).
gastric tumor (1 paper, 2024). "We found that compared with those in normal samples, gastric tumor samples had significantly increased TNF, NOX4, and LONP1 mRNA levels and decreased DUSP1 mRNA levels." (PMID 38758860, 2024).
glomerulosclerosis (1 paper, 2025). A hardening of the kidney glomerulus caused by scarring of the blood vessels. "•LONP1 is deficient in the glomerular endothelial cells, and plays a protective role in glomerulosclerosis progression." (PMID 41275592, 2025). "First, we used endothelial cell-specific LONP1 knockout mice to determine the adverse role of LONP1 deficiency in the development and progression of glomerulosclerosis." (PMID 41275592, 2025). "In this study, we found that LONP1 deficiency in endothelial cells disrupted the mitochondrial redox balance and aggravated glomerulosclerosis by protecting against SOD2 ubiquitination, while LONP1 overexpression alleviated cellular inflammatory injuries." (PMID 41275592, 2025). "And in the in vitro models, the LONP1 expression was correlated negatively with the concentration of stimulus, suggesting a key role of endothelial LONP1 in glomerulosclerosis." (PMID 41275592, 2025). "PAS staining revealed that endothelial cell-specific heterozygous knockout of LONP1 significantly aggravated pathological manifestations of glomerulosclerosis in 5/6Nx mice, whereas MnTBAP treatment reversed these pathological abnormalities." (PMID 41275592, 2025). "Taken together, our findings identify LONP1 as a therapeutic target for balancing glomerular redox, alleviating inflammation, and retarding glomerulosclerosis." (PMID 41275592, 2025). "•Endothelial cell-specific heterozygous knockout of LONP1 exacerbates glomerulosclerosis and CKD progression." (PMID 41275592, 2025). "Interestingly, endothelial cell-specific heterozygous knockout of LONP1 exacerbated glomerulosclerosis and aggravated renal function decline, proteinuria, hypertension and kidney inflammation in 5/6Nx mice." (PMID 41275592, 2025). "Furthermore, we investigated the effect of MnTBAP on glomerulosclerosis of 5/6Nx models exacerbated by LONP1 knockdown." (PMID 41275592, 2025). "However, further studies are needed to fully understand the protective role of LONP1 in glomerulosclerosis using endothelial cell-specific LONP1 knock-in mice." (PMID 41275592, 2025). "We suggest that endothelial LONP1, which stabilizes the SOD2 protein by protecting against SOD2 ubiquitination, exerts a protective effect on glomerulosclerosis induced by 5/6Nx and endothelial cellular injury models." (PMID 41275592, 2025). "Therefore, we hypothesize that an interaction between LONP1 and SOD2 may play an important role in the pathogenesis of glomerulosclerosis." (PMID 41275592, 2025).
Glucose intolerance (1 paper, 2022). Glucose intolerance (GI) can be defined as dysglycemia that comprises both prediabetes and diabetes. "We additionally confirmed reductions in Tfam and increases in LonP1 protein in β-Mfn1+/−Mfn2KO islets, correlating with the mtDNA depletion, glucose intolerance, and impaired GSIS observed in these mice." (PMID 35487893, 2022). "In contrast, β-Mfn1KOMfn2+/− mice, which develop mitochondrial structural alterations without glucose intolerance or mtDNA depletion, did not exhibit changes in Tfam and LonP1." (PMID 35487893, 2022).
head and neck cancer (1 paper, 2022). A primary or metastatic malignant neoplasm affecting the head and neck. "LonP1 has been found to be upregulated in head and neck cancer tissues, ranking in the top 1% in silico." (PMID 36362158, 2022).
hearing loss (1 paper, 2026). "To elucidate the relationship between LONP1 and lead exposure‐induced hearing loss, we examined the expression levels of LONP1 and its substrate HMGCS2 in the cochlea of lead‐exposed mice." (PMID 41215638, 2026).